NOTCH1 (notch receptor 1)
Diseases named in the same sentence as NOTCH1 in open-access papers (continued):
Sharing a sentence is not in itself a finding about the gene and the disease.
breast cancer (continued). "It was observed that NOTCH-1 activation is responsible for inducing the MMP-2 and MMP-9 expression and stimulation while lowering the regulation of NOTCH-1 involved in lowering the MMP-2 and MMP-9 activation to hinder cell progression in breast cancer and pancreatic cancer cells." (PMID 36359888, 2022). "Our findings also suggest that NOTCH1 and NOTCH2-driven breast cancers may represent a distinct biological form of breast cancer that is driven in part through the silencing of the PTEN tumor suppressor gene, in addition to the activation of oncogene targets such as MYC56." (PMID 33750924, 2021). "Despite the key role of EZH2 in repressing Notch signaling in T-ALL, a positive correlation between EZH2 and Notch was found in glioblastoma and breast cancer in which EZH2 directly binds Notch1 promoter, upregulating Notch1 expression without any change in H3K27me3 levels." (PMID 34680255, 2021). "Indeed, inhibition of Notch1 with siRNA or GSI DAPT enhanced growth inhibition and apoptosis induction by doxorubicin in breast cancer cells accompanied with the inactivation of NF-κB, induction of PTEN, and abolishing doxorubicin-induced upregulation of MDR-1." (PMID 34680255, 2021). "As Notch1 is a direct target of miR-139, further studies are needed to determine the additional role of miR-139-mediated down-modulation of the Snail/Slug-EMT axis in increasing E-cadherin levels to inhibit the invasive mesenchymal phenotype of breast cancer by targeting Notch1." (PMID 34070538, 2021). "In breast cancer (BC), some researchers suggested that the increased expression of SNHG7 could promote tumorigenesis and progression by EMT initiation and the activation of the Notch-1 pathway through interacting with miR-34a." (PMID 34714775, 2021). "In order to evaluate the oncogenic potential of NOTCH1 and NOTCH3 on breast cancer growth in vivo, we used the CRISPR-/Cas9-based genomic editing to prepare MCF-7 breast cancer cell-based KO cell lines lacking endogenous expression of either NOTCH1 or NOTCH3 genes and the corresponding proteins." (PMID 33775697, 2021). "Ablation of Notch4 but not Notch1 in the breast cancer cell lines MDA-MB-231 and Hs578T modulated sensitivity to genotoxic stress, which agreed with outcomes of overexpressing NIC4 and its role in modulating signaling cascades that confer protection from genomic damage." (PMID 32123583, 2020). "Notably, nanocomplex-assisted delivery of miRNA-34a induced apoptosis and suppressed migration and proliferation of breast cancer cells as well as reduced tumor growth in a xenograft mouse model via targeting signaling pathways autophagy-related, as CD44 and Notch-1." (PMID 32792960, 2020). "Therefore, we conclude that NOTCH1 hyperactivation promotes EMT, which might induce the formation of TNBC and basal-like breast cancer." (PMID 32591500, 2020). "In breast cancer cell lines, CCN6 overexpression inhibits cell growth and invasiveness, while CCN6 induces a epithelial to mesenchymal transition (EMT) and reduces tumor-initiating cells (TIC), which is mediated by the downregulation of Slug and inhibition of the Notch1 signaling pathway." (PMID 30237403, 2018). "Using the MMTV-PyMT mouse model, we show here that CCR7 and Notch1 cooperate and crosstalk within transformed mammary stem cell-like compartments, indicating that the CCR7-Notch axis may be a potential target for therapeutic intervention in breast cancer." (PMID 28137279, 2017). "Thus, Slug plays a key role in Notch1 signaling that modulates EMT and metastasis in breast cancer." (PMID 25645291, 2015). "Notably, culturing breast cancer cells with soluble Jagged1 protein induced EMT and increased their migration and invasion, which could be partially abolished by Notch1 knockdown." (PMID 25645291, 2015).
breast cancer (continued). "While Pin1 levels did not affect the clinical outcome in all patients, we found that in grade 3 breast cancer high Pin1 levels correlate with a worse outcome in patients with activated Notch1 signature (high NDT-high PIN1), but not in patients with low NDT signature expression." (PMID 24357640, 2014). "Previous studies suggest that human breast cancer cells become dependent on NOTCH1 in the absence of ERα or ERB2 signaling, raising the possibility that NOTCH inhibition may have therapeutic potential in TN human basal-like breast cancers." (PMID 22992387, 2012). "Moreover, some studies have demonstrated that C-terminal deletion of NOTCH1 intracellular domain (N1ICD) increases its instability without any effect on the amplification and recapitulation of N1ICD-dependent signaling; this contributes to the development of breast cancer." (PMID 37296801, 2023). "Interestingly, also in breast cancer, fewer CTCs have been reported for brain metastatic patients when analyzed by the CellSearch system, and those CTCs that were competent to colonize the brain as a distant target organ site were predominantly EpCAM-negative but EGFR, NOTCH1 and HPSE-positive." (PMID 30572662, 2018). "Notably, breast cancer tissue strong for ALDH1A1 expression displayed weak NOTCH1 staining compared to ALDH1A1 weak tumor tissue (P = 0.002), and the relationship between ALDH1A1 and NOTCH1 mRNA positivity was significant (Pearson correlation - 0.337, P = 0.014; Spearman’s rho - 0.376, P = 0.006)." (PMID 23767668, 2013). "Thus, NOTCH1 may induce Nanog expression in luminal progenitors and mammary tumor-initiating cells but not in the bulk differentiated tumor cells." (PMID 22992387, 2012). "First, we found that, in the RAB4A-high MDA-MB-231 breast cancer cells, NUMB expression is essentially absent and NOTCH1 and SOX2 expression are easily visualized by western blot." (PMID 39463384, 2024). "We also observed a significant negative correlation between NOTCH-1, NOTCH-2, and NOTCH-3 expression and their methylation, suggesting a potential epigenetic regulation of Notch receptors in breast cancer." (PMID 36476410, 2022). "However, the single silencing of Notch1 could be not sufficient to regain breast cancer cell sensitivity to doxorubicin; therefore, targeting multiple pathways including STAT3 and β-catenin together with Notch1 could provide a more synergistic action with doxorubicin." (PMID 34680255, 2021). "In our work, we found the Notch1 pathway was positively associated with ID4 expression both in MDA-MB-231 and MCF-7/Adr cells, and ID4 could activate CBF1 by directly binding to the CBF1 promoter region via combined with MyoD1, which was reported to be a negative transcriptor in breast cancer." (PMID 32328189, 2020). "We recently reported that in aggressive ER- breast cancer, EZH2 complexes with RelA/RelB and binds to the Notch1 promoter to activate transcription independent of its methyltransferase activity." (PMID 30022044, 2018). "Further study revealed that in TN breast cancer, EZH2 directly binds to the NOTCH1 promoter to active NOTCH1 signaling, independent of PRC2-mediated H3K27me3." (PMID 28415635, 2017).
breast cancer (continued). "Here we focused on the phosphorylation of Notch1, as expression of Notch 3 was restricted to MCF-7 breast cancer cells and not present in PC-3 prostate cancer cells, and the exact role of Notch3 in tumor progression is still under debate." (PMID 27281612, 2016). "DLL4, Notch1, IL-1R tI and VEGF were expressed in almost all breast cancer tissues irrespective of AR status." (PMID 24716804, 2014). "Continuous A_HSCORE (positive or negative) of Notch1, Notch4, JAG1, OB-R, VEGF and, VEGFR2 were not significantly different among breast cancers irrespective of their expression of ER, HER2 and PR." (PMID 24716804, 2014). "Here we show that NILCO components (Notch1, Notch4, JAG1, DLL4, leptin, OB-R, IL-1R tI) and target molecules (VEGF and VEGFR2) were co-expressed in breast cancer tissues, irrespective of ER, PR and, HER2 statuses." (PMID 24716804, 2014). "Our study showed there was not significant difference of Notch1 and N1IC expression in protein or mRNA levels in breast cancer specimen." (PMID 25420528, 2014). "In addition, protein levels of Notch1 and CD73 were significantly higher in TNBC cells (BT549, MDA-MB-231, and M453) than in non-TNBC breast cancer cells (T47D and MCF-7)." (PMID 37391408, 2023). "Corresponding to the successful DAPT therapy in a murine breast cancer model, treatment with DAPT decreased the migratory potential of HNSCC cells in this study, but this effect was not as strong as the siRNA-mediated NOTCH1 knockdown." (PMID 35205828, 2022). "In addition, transcription of Notch1 and Notch4 is activated by ETV4 in breast cancer cells, suggesting the involvement of ETV4 in stimulating Notch signaling." (PMID 34052833, 2021). "Moreover, the negative correlation between Notch1 and ATM activation has been observed in human breast cancer, and it contributes to the survival of Notch1 driven leukemia cells upon DNA damage." (PMID 33968932, 2021). "We showed that Notch1 can activate ERα-dependent transcription in the absence of estrogen, evading estrogen deprivation and that Protein Kinase C (PKC)α, a known marker of endocrine resistance, induces endocrine resistance in HR-positive breast cancer cells via Notch4." (PMID 37568775, 2023). "With and without EDTA exposure, EP1238Y antibody identified Notch1 protein of ~125 kDa, corresponding to the approximate size of NTM of Notch1; D3B8 antibody detected N1-ICD-V1754 of ~110 kDa in NSCLC NCI-H23, NCI-H522 and breast cancer MCF-7 cells after EDTA treatment." (PMID 25653136, 2015).
glioma (242 papers, 2009 to 2026). A benign or malignant brain and spinal cord tumor that arises from glial cells (astrocytes, oligodendrocytes, ependymal cells). "Both PRO and MES eGBO‐derived tumors had broad expression of NOTCH1, which is commonly upregulated in glioma tumor‐initiating cells, and BCAN, which encodes an extracellular matrix protein found in human gliomas." (PMID 39836549, 2025). "lncRNA FOXD2-AS1, TATA-Box binding protein-associated factor 1 (TAF-1), and Notch receptor 1 (NOTCH1) were found to be significantly upregulated in glioma tissues and GSCs." (PMID 38967893, 2024). "Oligodendroglioma (Omut-IDH,codel-1p/19q,G3), in which TERT (3/4 Patients), CIC (3/4 Patients), FUBP1 (1/4 Patients), and NOTCH1 promoter (1/4 Patients), which corroborates the frequency of mutations in these genes in patients with high-grade gliomas." (PMID 39767683, 2024). "Cases in G1 group were rich in IDH, CIC, and NOTCH1 mutations that have been confirmed to be enriched in low grade glioma." (PMID 37322408, 2023). "Elevated levels of vasorin have been demonstrated to bind to and prevent the degradation of Notch1 in glioblastoma, and the resulting augmentation of Notch1 stability is thought to account for the vasorin‐associated aggressiveness of glioma." (PMID 35170203, 2022). "Among Notch receptors and ligands, Notch1 and its ligand Jagged1 have been found to be associated with the tumorigenesis and recurrence of glioma." (PMID 36235115, 2022). "Then, we quantified the expression of lncRNA FOXD2‐AS1, TATA‐box binding protein associated factor 1 (TAF‐1) and NOTCH1 in glioma tissues and GSCs, as well as the expression of GSC stem markers, OCT4, SOX2, Nanog, Nestin and CD133 in GSCs." (PMID 35419917, 2022). "Several publications suggested that activation of the NOTCH1 pathway is associated with glioma cell properties in the PVN, including cellular stemness." (PMID 33579922, 2021). "For example, higher expression of Achaete-Scute Family BHLH Transcription Factor-1 (ASCL1), DLL1, Notch1, Notch3, Notch4, and Hey1 is associated with high-grade glioma and a worse prognosis." (PMID 36643842, 2021). "This interaction led to a positive feedback loop governed by SOX2 and 9 on glioma cells, which decreased Notch1 promoter methylation, leading to its transcription to reinforce glioma–neuron association." (PMID 33805316, 2021). "The downregulation of the NOTCH1 pathway exhaust the pool of glioma cells associated with perivascular microenvironment and diminishes the niche protective action." (PMID 34204510, 2021). "We first explored the alteration frequency of NOTCH1 in different type of brain tumors (n = 1300) (cBioPortal) and found the major type of genomic alterations in glioma was mutation or amplication." (PMID 30170559, 2018). "Association of Notch1 with the mitochondria has also been observed in glioma stem cells, T-cells, and macrophages." (PMID 30564555, 2018). "However, the involvement of NOTCH1 in the EMT of glioma cells and the underlying mechanisms are unclear." (PMID 40530904, 2025). "Notably, it has been documented that Notch1 displays abnormal expression in gliomas of all grades, and overexpression of Notch1 is linked to a poorer survival outcome." (PMID 40100070, 2025). "Furthermore, NOTCH1 mutations are found in approximately 8.5% of gliomas, with higher mutation frequencies in lower-grade gliomas." (PMID 40564017, 2025). "Meanwhile, Notch1 pathway‐related genes, including Maml2, Ccn3, Fat4, Cdh6, and Ptp4a3, exhibited similar expression trends and may be intimately linked to glioma development." (PMID 39544152, 2024).
glioma (continued). "The AKT arm of this pathway is consistent with what has been described in glioma stem cells and Drosophila neuroblasts, whereby Notch1 associates with PTEN-induced kinase 1 (PINK1) on the mitochondrial surface to modulate mitochondrial function, and activates mTORC2/AKT signaling." (PMID 30564555, 2018). "The Notch signaling pathway comprises four receptors: Notch1, which may function as either a tumor suppressor or oncogene; Notch2, considered a prognostic marker in glioma; Notch3, which promotes glioma cell proliferation; and Notch4, associated with increased tumor aggressiveness." (PMID 40942013, 2025). "Very similarly, the overall survival of the glioma patients with high-level of Notch1 expression was markedly lower than that of patients with low-level of Notch1 expression, consistent with the report of Engh JA who previously implicated Notch1 as a prognostic factor for glioma patients." (PMID 31277684, 2019). "Silencing Notch1 can inhibit the proliferation of glioma cells and promote the autophagy of glioma cells." (PMID 41596253, 2026). "Knocking down PDGF‐D in the LN18 glioma cell line reduced the expression of phosphorylated p65 and NOTCH1 and inhibited clonal proliferation, migration, invasion, and the EMT program." (PMID 40530904, 2025). "β-1,4-GalT-V regulates VEGF-independent angiogenesis by generating LacCer and galactosylation of Notch-1, regulating production of glioma-like stem cell differentiation into endothelial cells and promoting tumorigenesis." (PMID 40869407, 2025). "NOTCH1 is upregulated in human glioma cells and its high expression levels correlate with tumor occurrence and development." (PMID 40530904, 2025). "Notch-1 is an N-glycosylated protein and is required in the regulation of endothelial trans-differentiation of glioma stem-like cells into endothelial cells." (PMID 40869407, 2025). "In glioma-initiating cells (GICs), autophagy suppresses stemness and tumorigenicity by inhibiting the activation of the pro-stemness Notch1 signaling pathway." (PMID 40886002, 2025). "Recent research studies have explored the expression patterns of Notch1 in gliomas, yielding diverse conclusions regarding its impact on tumour progression and prognosis." (PMID 40100070, 2025). "In glioblastoma, miR-139 inhibits Notch1/Hes1, thereby suppressing the activation of the Wnt/β-catenin pathway, thus inhibiting glioma stem cell stemness and tumorigenesis." (PMID 40755759, 2025). "Although the role of Notch1 signalling in glioma has been the focus of increasing research efforts, its expression in glioblastomas (GBMs) remains a subject of debate." (PMID 40100070, 2025). "For instance, silencing circNFIX in glioma models has dramatically reduced tumor growth via miR‐34a‐5p/NOTCH 1 inhibition." (PMID 40761890, 2025). "Several genes included in our signature, notably NOTCH1, NES, E2F1 and EGFR, have been implicated in glioma adaptation to temozolomide (TMZ) therapy, where changes in their expression or activity influence stemness, invasion and drug resistance." (PMID 41375052, 2025). "Considering the central role that Notch1 signalling plays in glioma cells, approaches targeting the inhibition of Notch1 hold great promise as a potential avenue for the treatment of GBM." (PMID 40100070, 2025). "Conversely, RBM8A enhances glioma invasiveness by upregulating Notch1 and STAT3 transcription, thereby activating the Notch/STAT signaling axis." (PMID 40942013, 2025). "From the figure, it is evident that in both groups of gliomas, the NOTCH1 and SOX2 genes were most affected by changes." (PMID 40679044, 2025). "Collectively, these studies reveal that β-1,4-GalT-V can regulate a VEGF-independent pathway to induce angiogenesis via recruiting LacCer and Notch-1 in addition to the trans-differentiation of glioma stem-like cells into endothelial cells." (PMID 40869407, 2025). "In gliomas with Jagged1 expression, the levels of Notch1, c‐Myc, and PD‐L1 were significantly elevated." (PMID 40656546, 2025).